KL (klotho)
Diseases named in the same sentence as KL in open-access papers (continued):
Sharing a sentence is not in itself a finding about the gene and the disease.
endothelial dysfunction (continued). "s-Klotho attenuates endothelial dysfunction through several mechanisms." (PMID 40407975, 2025). "When Klotho is deficient, FGF23-stimulated NO synthesis is blunted, and ROS degradation is impaired, resulting in increased oxidative stress and reduced NO bioavailability—key features of endothelial dysfunction." (PMID 41303567, 2025). "Beyond being a biochemical marker, phosphate overload triggers NOX-derived reactive oxygen species (ROS), activates Wnt/β-catenin and TGF-β signaling, and disrupts the FGF23–Klotho axis, promoting endothelial dysfunction, vascular calcification, and left ventricular hypertrophy (LVH)." (PMID 41516280, 2025). "Klotho deficiency in CKD may enhance renal tubule and vascular cell senescence, leading to endothelial dysfunction." (PMID 39544340, 2024). "In the context of chronic diseases such as DKD, where patients experience ongoing endothelial dysfunction, the cumulative impact of long-term ROS reduction and Klotho upregulation may only become apparent after extended PTX therapy." (PMID 39765800, 2024). "Defects in Klotho expression in mice result in a syndrome that is similar to human aging, including Mönckeberg-type arteriosclerosis from the aorta to small arterioles, impairments in angiogenesis and vasculogenesis and endothelial dysfunction." (PMID 37274332, 2023). "The authors hypothesised that their results may be related to increased Klotho protein levels or activity of the protein which could protects against microvascular inflammation and endothelial dysfunction that drive onset and progression of retinopathy." (PMID 33225726, 2020). "Klotho plays a role in the protection against endothelial dysfunction." (PMID 30943913, 2019). "The interactions among KLOTHO, TNFα, NF-kB and inflammatory processes are not restricted to the kidney, with studies suggest that endothelial dysfunction observed in mice deficient in KLOTHO is reversed by KLOTHO reposition." (PMID 25961830, 2015). "In experimental models, the absence of Klotho gene is associated with endothelial dysfunction and diffuse vascular calcification." (PMID 22121479, 2012). "In studies involving Klotho-deficient mice, the absence of Klotho leads to accelerated endothelial dysfunction and vascular aging, characterized by increased stiffness of the arterial walls and impaired NO bioavailability, which is critical for maintaining healthy blood vessel function [1366, 1367]." (PMID 40407975, 2025). "Also, experimental models have reported, that the absence of the klotho gene is linked to endothelial dysfunction and diffuse vascular calcification." (PMID 39616409, 2024). "Moreover, some studies have revealed that Klotho may work as an important humoral factor involved in oxidative stress regulation, endothelial dysfunction, cell proliferation, and apoptosis." (PMID 28407763, 2017). "Given their possible involvement in key molecular pathways—ranging from oxidative stress and low-grade inflammation to endothelial dysfunction, altered mineral metabolism and tissue remodeling—RBP4, LCN2, ApoM, Klotho and MGP represent more than isolated biomarkers." (PMID 41303567, 2025).
Alzheimer disease (53 papers, 2015 to 2026). A progressive, neurodegenerative disease characterized by loss of function and death of nerve cells in several areas of the brain leading to loss of cognitive function such as memory and language. "In the field of neurology, especially in diseases associated with cognition, overexpressed klotho protein is capable of ameliorating cognitive impairments represented by Alzheimer’s disease." (PMID 40452763, 2025). "Klotho deficiency has been associated with several neurological disorders, including multiple sclerosis, Alzheimer’s disease, amyotrophic lateral sclerosis, and Parkinson’s disease." (PMID 40134808, 2025). "Conversely, individuals that carry mutations that result in increased levels of klotho are protected from Alzheimer’s disease and cognitive decline." (PMID 40156002, 2025). "In humans, carrying a genetic variant of KLOTHO or having higher levels of klotho has been associated with better cognition or decreased risk of dementia in aging and in Alzheimer’s disease." (PMID 37746149, 2023). "Pathogenesis of Alzheimer’s disease which predominantly includes damage to neurons associated with amyloid-β and glutamate can be prevented by preliminary therapy of neurons with Klotho protein." (PMID 37425590, 2023). "Klotho deficiency has been associated with many neurological conditions, including multiple sclerosis, Alzheimer’s disease, amyotrophic lateral sclerosis, and Parkinson’s disease." (PMID 37425590, 2023). "A Klotho gene variant denoted KL-VS (2 amino acid substitutions in the protein) appears to provide some protection against Alzheimer’s disease, but only in the heterozygous state." (PMID 35903083, 2022). "Therapeutic approaches increasing KL gene expression can prevent further neurodegeneration and memory loss associated with aging and Alzheimer's disease (AD)." (PMID 35274439, 2022). "The KL-VS haplotype of the Klotho gene has been associated with reduced risk of Alzheimer’s disease and dementia." (PMID 34158479, 2021). "Elevated levels of the longevity factor klotho suppress aging, enhance cognition, and promote synaptic plasticity and neural resilience against aging and Alzheimer’s disease (AD)-related pathogenic proteins." (PMID 27714549, 2017). "Klotho KL is an aging factor that has been associated with Alzheimer's Disease (AD) risk." (PMID 42039664, 2026). "KLOTHO-VS (KL-VS) heterozygosity, a variant of the KLOTHO gene, and its encoded protein, α-Klotho, are associated with brain health and show neuroprotective potential against Alzheimer’s disease (AD)." (PMID 41163083, 2025). "This notion becomes relevant given the generalized therapeutic benefits deemed to be associated with the elevation of wild-type Klotho levels or its activities deemed to confer an advantage against neurological and other cognitive disorders including Alzheimer’s disease." (PMID 40083947, 2025). "The mouse Klotho null mutation may be used as a study model for age-related retinal degeneration and Alzheimer’s disease." (PMID 40373038, 2025). "Interestingly, there are some evidences indicated that Klotho upregulation can attenuate the Alzheimer’s disease-related pathology including memory deficiency, amyloid beta accumulation, and tau phosphorylation." (PMID 40373038, 2025). "Transcriptomic profiling shows that Klotho knockout perturbs brain short non-coding RNAs, such as microRNA and tRNA fragments, in both neurons and glia, that mimics the changes associated with Alzheimer’s disease and aging in humans and murine models." (PMID 38862813, 2024). "In addition, elevated levels of Klotho in a mouse model of Alzheimer’s disease (AD) have been associated with reduced cognitive deficits and improved cognition in old and young mice." (PMID 37894946, 2023).
Alzheimer disease (continued). "What is the association between Klotho protein levels in cerebrospinal fluid (CSF) and plasma, heterozygosity status of the KL-VS haplotype, and amyloid and tau burden among cognitively healthy controls and patients with Alzheimer disease (AD)?" (PMID 36413367, 2022). "Autophagy is impaired in the brains of patients and animal models with Alzheimer’s disease, and this defect is associated with low Klotho expression and may be related to amyloid-β deposition." (PMID 34737707, 2021). "Klotho-VS heterozygosity (KL-VShet) is associated with reduced risk of Alzheimer’s disease (AD)." (PMID 34158479, 2021). "In fact, recent studies have shown that Klotho might prevent the development of Alzheimer's disease associated with aging by inhibiting insulin/IGF-1 signaling and, consequently, oxidative injury in the brain." (PMID 26599613, 2015). "Finally, recent studies also suggest that Klotho might prevent the development of Alzheimer's disease (AD) associated with aging, probably by inhibiting insulin/IGF-1 signaling and, consequently, oxidative injury in the brain in a murine model of AD." (PMID 26599613, 2015). "Future studies should explore these mechanistic aspects in both in vitro and in vivo models to provide deeper insights into Klotho’s therapeutic potential for Alzheimer’s disease." (PMID 40156002, 2025). "Recent studies have also highlighted the potential neuroprotective role of Klotho in Alzheimer’s disease and other neurodegenerative conditions by modulating synaptic plasticity and reducing amyloid beta deposition." (PMID 40894259, 2025). "S-Klotho levels are downregulated in a variety of diseases, including renal diseases, Alzheimer’s disease, chronic obstructive pulmonary disease, certain tumors, and vascular diseases." (PMID 40333908, 2025). "It has been found that Alzheimer’s disease patients have lower Klotho concentrations in their cerebrospinal fluid than healthy individuals." (PMID 40134808, 2025). "The systemic effects of Klotho indicate its implication in several disease pathophysiologies other than kidney, including cardiovascular diseases, alzheimer’s disease, cancer, inflammatory bowel disease, liver disease and aging-associated diseases." (PMID 40119098, 2025). "Klotho has a prominent protective role against neurodegenerative diseases, especially Alzheimer’s disease." (PMID 39272986, 2024). "Mean cerebrospinal fluid Klotho levels are significantly lower in older adults compared with younger individuals (P = .005) and in patients with Alzheimer's disease (P = .02)." (PMID 38213484, 2024). "Klotho CSF levels and tissue expression in the brain decline with aging and early Alzheimer’s disease." (PMID 39272986, 2024). "One study found lower levels of klotho in the cerebrospinal fluid of Alzheimer’s disease (AD) patients, suggesting a potential link between lower klotho levels and cognitive function." (PMID 39563739, 2024). "A cross-sectional observational study on 94 subjects from Oregon Alzheimer’s Disease Center reported that the levels of Klotho protein in both serum and CSF were correlated with Mini-Mental State Examination (MMSE) scores." (PMID 37914711, 2023). "The cerebrospinal fluid Klotho concentrations are lower in Alzheimer’s disease, probably leading to a poor synaptic and cognitive functions." (PMID 37560310, 2023). "In mouse models of aging and Alzheimer’s disease, systemic elevation of klotho boosts cognitive function and enhances long-term potentiation." (PMID 37746149, 2023). "A longitudinal study showed that older adults with Alzheimer’s disease had significantly lower cerebrospinal fluid (CSF) Klotho concentrations than older adults with normal cognition." (PMID 37914711, 2023). "Pretreatment of patients with Alzheimer’s disease with Klotho protein has been shown to decrease neuronal injury related to amyloid and glutamate." (PMID 37425590, 2023).
Alzheimer disease (continued). "Increased levels of Klotho in the preliminary grades of the disease can express a curative master plan to reduce further damage and can also improve the consequences for Alzheimer’s disease patients who are older in age." (PMID 37425590, 2023). "A study done in Baltimore demonstrated that there are lower Klotho levels in CSF of Alzheimer’s disease compared to the control group, lower levels in older adults compared to younger adults, and higher levels in males than females." (PMID 37425590, 2023). "The activation of ROS signaling and oxidative stress in aged brains is involved in the development of Alzheimer’s disease and antioxidant-neuroprotective Akt-mediated effects of Klotho have been depicted." (PMID 36829798, 2023). "Another important discovery in that study was that patients with Alzheimer’s disease had lower CSF Klotho concentrations than those with normal cognition." (PMID 37425590, 2023). "The level of klotho, an anti-aging protein, decreases with aging and aging-related diseases such as cardiovascular disease, Alzheimer disease, kidney disease, chronic obstructive pulmonary disease and cerebrovascular diseases." (PMID 36831102, 2023). "This natural compound increased the expression of ADAM10 and s-Klotho, and was protective in a mouse model of Alzheimer’s disease (see section 10.4)." (PMID 35903083, 2022). "The gene product of KL is known to control the brain-immune system interface in the choroid plexus and to regulate autophagy in Alzheimer’s disease." (PMID 35625844, 2022). "Primarily, we found several aging (klotho, major vault 1, gelsolin, huntingtin, and fragile X mental retardation protein) and Alzheimer’s disease (ADAM10, apoE receptor, ChAT, APP, and PSEN1; most of these are also involved in aging) related sequences." (PMID 32449011, 2020). "Klotho is a protein involved in suppressing aging and is significantly elevated in the CSF of Alzheimer’s disease patients." (PMID 31063132, 2019). "Emerging evidence suggests that alpha-processing single transmembrane proteins, amyloid precursor protein (APP) and anti-aging protein Klotho, are likely to be involved in the progression of Alzheimer’s disease (AD)." (PMID 29163135, 2017). "In a mouse model, inverse correlation was shown between klotho expression and Alzheimer's disease phenotype." (PMID 27375434, 2016). "In the 3xTg-AD mouse model of Alzheimer's disease, both, the mRNA and protein levels of klotho declined more rapidly than in age-matched control animals." (PMID 26599613, 2015). "Our results highlight the direct neuroprotective effects of KLOTHO, underscoring its potential to improve brain function during aging and supporting its promise as a therapeutic target for age-related neurodegenerative diseases such as Alzheimer’s disease." (PMID 40156002, 2025). "Having established that KLOTHO prevents the increase of several hallmarks of senescence observed in Alzheimer’s disease, we here sought to determine whether KLOTHO provides resistance to β-amyloid-induced neuronal degeneration and death." (PMID 40156002, 2025). "Several studies demonstrated the protective effects of Klotho in Alzheimer’s disease (AD) patients." (PMID 40373038, 2025). "In the APP/PS1 mice model of alzheimer's disease, Klotho upregulation boosts amyloid clearance and cognition by inhibiting NLRP3, encouraging microglia transformation, and managing the expression of the Aβ transporter, ultimately improving Aβ clearance in the brain." (PMID 40119098, 2025). "It has been shown that CSF Klotho levels are lower in individuals with Alzheimer’s disease compared to controls, lower in older adults compared to younger adults, and lower in females compared to males, suggesting a potential role of Klotho in brain aging and cognition." (PMID 40799848, 2024). "In addition, decreased expression of the klotho protein is involved in the development of chronic obstructive pulmonary disease and Alzheimer’s disease." (PMID 38696398, 2024).
Alzheimer disease (continued). "Klotho has also been studied as a therapeutic target for Alzheimer’s disease." (PMID 40799848, 2024). "Besides, the relationship between cognitive functions and Klotho was also suggested in schizophrenia, Alzheimer’s disease, and multiple system atrophy." (PMID 37560310, 2023). "Previous studies showed that serum klotho levels were decreased in humans with aging and with age-related diseases, such as cardiovascular diseases (including hypertension), chronic kidney disease, cancer or Alzheimer disease." (PMID 36831102, 2023). "In this article, we aim to further explore the associations between the Klotho gene and dementia and try to help build a platform so that work can be done to investigate the therapeutic potential of Klotho for neurodegenerative conditions such as Alzheimer’s disease." (PMID 37425590, 2023). "Besides, the relationship between Klotho and cognitive functions has been explored in general older adults and various diseases, containing schizophrenia, Alzheimer’s disease and cerebrovascular diseases." (PMID 37560310, 2023). "In mouse models of Alzheimer’s disease, Klotho overexpression is beneficial." (PMID 35903083, 2022). "This case-control study assesses concentrations of Klotho protein in cerebrospinal fluid and plasma among cognitively healthy controls and patients with Alzheimer disease (AD) and correlates these findings with KL-VS heterozygosity status and amyloid and tau burden." (PMID 36413367, 2022). "For example, Klotho (KL) is a gene that plays an important role in Alzheimer’s disease." (PMID 35163298, 2022). "Klotho expression in the brain is decreased in aging subjects and early Alzheimer’s disease." (PMID 35903083, 2022). "Elevation of brain klotho also could reverse synaptic and cognitive impairments in the mouse model of Alzheimer’s disease." (PMID 32612508, 2020). "The high expression of Kl throughout plexus development and into the adult suggests some protective effect on plexus epithelial cells themselves, and also on other CNS cells— especially considering evidence that KLOTHO protein levels in the CSF are decreased in Alzheimer's disease humans." (PMID 25784848, 2015). "Interestingly, in the cerebellum, where the effects of the Alzheimer's disease are more discrete than in other areas, the expression of s-KL and m-KL declined at all ages at a similar rate than in control animals." (PMID 26599613, 2015). "We have studied whether klotho expression in the CNS was influenced during aging by a pathological process, such as Alzheimer's disease, and whether a healthy lifestyle, such as voluntary moderate continuous exercise, could also influence klotho expression." (PMID 26599613, 2015). "We also studied whether klotho expression in the CNS was influenced by aging, Alzheimer's disease (AD), or a healthy lifestyle, such as voluntary moderate continuous exercise." (PMID 26599613, 2015). "Hence, a major neuroprotective role is played by Klotho protein patients with Alzheimer’s disease." (PMID 37425590, 2023). "Klotho elevation could promote synaptic plasticity and cognition by enriching GluN2B subunit of NMDARs at synapses in the hippocampus and frontal cortex in both normal and Alzheimer disease (AD) model mice." (PMID 32612508, 2020). "Moreover, the protective effect of klotho extends beyond DKD in other pathological conditions, including cardiovascular diseases, alzheimer's disease, cancer, inflammatory bowel disease, and liver disease." (PMID 40119098, 2025). "A negative correlation has been reported between Alzheimer’s disease and the levels of Klotho protein in the CSF." (PMID 37425590, 2023). "Klotho has also been shown to inhibit the activation of the NLRP3/caspase-1 signaling pathway, a pathway stimulated by β-amyloid and thought to have an important role in Alzheimer’s disease." (PMID 37425590, 2023). "Similarly, Klotho was related to IGF1 signalling inhibition, thus to neuroprotection in Alzheimer’s disease mouse model." (PMID 37985893, 2023).
Alzheimer disease (continued). "Klotho is an amyloid precursor protein (APP)- and APP-like Protein 2 (APLP2)-dependent gene that is regulated by the large secreted ectodomain fragment soluble (APPsβ), and therefore, it may play a role in the development of Alzheimer’s disease." (PMID 26599613, 2015). "We also analyzed whether the reduction observed in the expression of the s-KL and m-KL transcripts in the different brain areas during non-pathological aging was also observed in pathological aging as happens in neurodegenerative disorders like Alzheimer's disease." (PMID 26599613, 2015).